CXCR5 (C-X-C motif chemokine receptor 5)
Diseases named in the same sentence as CXCR5 in open-access papers (continued):
Sharing a sentence is not in itself a finding about the gene and the disease.
cancer (continued). "The endpoint of facilitating metastasis may arouse enthusiasm in pursuing CXCL13/CXCR5 as a potential target for cancer therapy." (PMID 34947813, 2021). "However, recent gene knockdown/suppression findings including the neutralization of overexpressed CXCL13 and/or CXCR5 activities have shown the therapeutic potential/validation of this pathway in many kinds of human cancers [22, 33−35]." (PMID 34922542, 2021). "Elevated levels of CXCL13 and its cognate receptor, CXCR5, are found in many types of cancer cells." (PMID 32847038, 2020). "TCF1+ TILs and CXCR5+ TILs have also been observed in human cancer TME; however, whether the human TCF1+ or CXCR5+ TILs resemble their mouse counterparts remains highly controversial." (PMID 33329692, 2020). "CXCR5 is a specific CXCL13 receptor that mediates CXCL13-regulated cancer functions." (PMID 32847038, 2020). "In contrast to most chronic viral infections and cancer, autoimmune and inflammatory CXCR5+ CD8 T cells likely promote the disease state, although the mechanisms that alter or advance GC reactions, in addition to direct cell lysis, may be similar." (PMID 31275308, 2019). "Similarly, CXCR5+ CD8 T cells isolated from PBMCs of cancer patients proliferate more than CXCR5- CD8 T cells after TCR stimulation." (PMID 31275308, 2019). "CXCL13 could activate many signaling pathways in cancer cells through binding to its receptor CXCR5, a member of G protein coupled receptor (GPCR) superfamily." (PMID 30723697, 2018). "Notably, upon combination therapy, ASPH-MYC and downstream PD-L1/PD-1 signals were blocked; CTLs secreted CXCL13 could bind to CXCR5 on cancer cells and produce cytotoxicity against them efficiently." (PMID 35392977, 2022). "The CXCL13/CXCR5 axis makes pivotal contributions to the initiation and progression of tumors, and therefore may serve as an attractive therapeutic target for related malignant neoplasms." (PMID 34947813, 2021). "Therefore, the CXCL13/CXCR5 axis plays a key role in regulating the proliferation of many cancer cells and could be a valuable therapeutic target." (PMID 34947813, 2021). "On the contrary, suppressing CXCR5 could reduce cancer growth and liver metastasis." (PMID 33324682, 2020). "What might the biological role of CXCR5/CXCL13 interactions be in the case of human cancers?" (PMID 18781150, 2008). "In broader terms, tonsillar CXCR5+ CD8+ T cells resemble the “stem-like” PD-1+TCF1+CXCR5+ CD8+ populations described in chronic viral infections and cancer." (PMID 41499499, 2026). "Previous research shows that the CXCR5-expressing follicular CD8+ T cells migrate into B cell follicles and are important in the response to chronic viral infection and cancers." (PMID 40091833, 2025). "The heatmap displayed that GPX4 expression was highly correlated with the levels of numerous chemokines and chemokine receptors, such as CXCL16, CCL28, CX3CL1, CCL5, CCR10, CXCR5, and CXCR3, across the majority of cancer types." (PMID 41142608, 2025). "Specifically, chemokines such as CXCL9, CXCL10, and CXCL11 and chemokine receptors such as CXCR5, CCR4, CCR8, and CCR1 were positively correlated with IGF2BP3 expression in various cancer types." (PMID 36761737, 2023). "Given the central role of PD-1 inhibition in cancer immunotherapy, this also pertains to PD-1-expressing components of the CXCL13/CXCR5-axis." (PMID 36836910, 2023). "One such cargo, onco-miRNA miR-494-3p, found in various cancers, targets the PI3K/AKT signaling pathway to promote lung cancer progression and regulates CXCR5 to promote cancer growth and EMT in glioblastoma, prostate cancer, and hepatocellular carcinoma." (PMID 37298370, 2023). "In cancer cells, CXCL13/CXCR5 regulates cell invasion and migration, and those are in Gαq and Gαi2 /Rac dependent manner." (PMID 35053457, 2022). "Asbestos can induce inflammatory changes, including increase in MMP7, CXCR5, CXCL13, and CD44, and this chronic inflammation can lead to chronic diseases, such as cancer." (PMID 35036082, 2022).
cancer (continued). "CXCR5+CD8 T cells are a newly developing area of study that allow for a unique perspective and growth in the fields of cancer research and immune checkpoint blockade." (PMID 36314014, 2022). "CXCR5+CD8 T cells in pancreatic cancer express both PD-1 and TIM3 suggesting a Tex phenotype that varies from other cancers." (PMID 36314014, 2022). "CXCR5+CD8 T cells have cytotoxic and proliferative capacity within cancer ranging from liquid to solid tumors." (PMID 36314014, 2022). "Tfr cells, generally defined as CXCR5+FOXP3+BCL6±ICOS± CD4+ cells, have been detected intratumorally in various cancers with limited assessments of their prognostic value." (PMID 36077836, 2022). "CXCR5+HLA-DR+CD8+ T cell populations shared phenotypic profiles of Tscm, as described in cancer and in chronic viral infection such as HIV." (PMID 34283810, 2021). "In a variety of malignant tumors, CXCL13 interacts with its receptor CXCR5 to promote carcinogenesis, development, and metastasis." (PMID 34922542, 2021). "CD8 + CXCR5 + T cells are a subset of CD8 + T cells, which have potential cytotoxic effects in chronic viral infections and cancers." (PMID 33585256, 2020). "High levels of CXCR5 and MEF2C expression are typical for both cell lines, according to Broad-Novartis Cancer Cell Line Encyclopedia." (PMID 27909439, 2016). "In conclusion, we demonstrate that CD40 expression upregulates the chemokine receptor CXCR5 and promotes MDSC migration toward and accumulation within cancer." (PMID 26462153, 2015). "This correlates with the CXCR5 expression in these cells and suggests a critical role for the CXCR5-CXCL13 axis in the recruitment of MDSC to cancer." (PMID 26462153, 2015). "Recently, CXCR5 has been found to be involved inremodeling of extracellular matrix (ECM) in various types of cancer, including colon andprostate cancer." (PMID 21533157, 2011). "Akin to chronic viral infection and cancer systems, pop3 (KLRG1-CD62Lhi) exhibits the characteristics of stem-like progenitor CD8 T cells (high Tcf7, Slamf6, and Cxcr5 expression), whereas pop4 (KLRG1+CD62Lhi) closely resembles a transitory subset (elevated Tbx21, low Tcf1, and Tox expression)." (PMID 39975082, 2025). "Furthermore, in most cancers, MHS were positively correlated with the expression of chemokine receptor genes such as CX3CR1 and CCR9 and negatively correlated with CXCR5 (P < 0.05)." (PMID 41174507, 2025). "As enhanced TFH cell differentiation in a TMBHigh mouse cancer model has been shown to induce larger TLSs and superior B-cell recruitment, we next determined the density of CD4+CXCR5+PD1+FoxP3− TFH cells in HGSOC and NSCLC samples using multiplex immunofluorescence." (PMID 38514660, 2024). "Therefore, all these findings suggest CXCR5 and CXCL13 as good prognostic markers of TILs against cancer cells as both confirmed in animal and human studies associated with a better clinical outcome." (PMID 39001456, 2024). "Notably, our model resembles the cancer-immunity cycle initially proposed by Chen and Mellman with the important distinctions of the cycle happening directly in the TME and CXCR5+ B cells functioning as its major APC." (PMID 37435085, 2023). "Both CD163 and CD4 + CXCR5 can be regarded as prognostic predictors for CRC patients to facilitate the evaluation of cancer prognosis and TME status, thereby optimizing individualized treatment plans and improving cancer patient survival." (PMID 36859111, 2023). "Chemokine, CXCR5, knockdown has proven to have negative prognostic value in certain cancers and cell lines." (PMID 36314014, 2022).
cancer (continued). "In lymphoid organs as well as cancers, Tfh cells are important regulators of antigen-specific B cell responses, since they produce the B cell chemoattractant CXCL13 to which B cells respond through its receptor CXCR5." (PMID 36077836, 2022). "In response to combination therapy, CXCL13 produced by ASPH+ expressing HCC or TNBC cell was capable of recruiting immune cells, especially CXCR5+/CD8+ TILs (including a proportion of CTLs), to participate in forming TLSs and to execute cytotoxicity against cancer cells." (PMID 35392977, 2022). "Human cancer cell lines that originated from the liver, colon, and kidney were also negative for CXCR5." (PMID 33431832, 2021). "We first confirmed CXCL13 expression in NSCLC patient blood and cancer tissues and the absence of CXCR5 expression in normal CD3 T cells." (PMID 34553036, 2021). "In addition, CXCL13/CXCR5 axis activates the phosphatidylinositol‐3 kinase (PI3K)/AKT pathway, leading to invasion and migration of cancer cells." (PMID 32314548, 2020). "The chemokine ligand CXCL13 and its chemokine receptor CXCR5 are among the key chemotactic factors that play crucial roles in the biology of cancer cells, and the CXCL13/CXCR5 signaling axis makes pivotal contributions to the development and progression of several human cancers." (PMID 33213490, 2020). "Histopathological analysis of these samples showed significantly higher expression of CXCR5 (p<0.001) in carcinomas (i.e., SCCs and ACs) relative to non-neoplastic lung tissue." (PMID 25271023, 2014). "CXCL13 upregulation by tumors induces migration, signaling and functional changes by CXCR5-expressing immune cells, but the specific functional capacity of CXCR5+CD8 T cells versus other CXCR5-expressing cells, including B cells and tumors, is poorly characterized in cancer." (PMID 36314014, 2022). "Thus, complex network involving tumoral and stromal (immune) CXCL13 and CXCR5 integrate to promote cancer cell autonomous and non-autonomous responses, highlighting autocrine, paracrine and endocrine interactions in dictating aggressive cancer phenotypes." (PMID 35392977, 2022). "CXCR5 could be also detected in human lung tumors, however its levels were not significantly different between cancer and normal tissue." (PMID 31354634, 2019). "Interestingly, we did not detect any CXCR5+ T lymphocytes in the carcinoma tissues, in contrast to the unaffected tissues." (PMID 29020986, 2017). "Thus, the complex networks of cellular interactions involving tumoral CXCL13 and CXCR5 integrate to promote cancer cell autonomous and non-autonomous responses, highlighting the relevance of autocrine and paracrine interactions in dictating the cancer phenotype." (PMID 31354634, 2019). "An apparent trend towards lower chemokine receptor expression by T lymphocytes from carcinoma tissue was observed for the receptors CCR3 and CX3CR1, whereas CXCR5 was not expressed at all by T lymphocytes from carcinoma tissue." (PMID 29020986, 2017).
infectious disease (7 papers, 2013 to 2025). A disorder directly resulting from the presence and activity of a microbial, viral, or parasitic agent in humans. "Based on the crucial roles the CXCL13:CXCR5 axis plays in both physiologic and pathologic immunity, it is not surprising that this axis has been implicated in the pathogenesis of a number of infectious diseases." (PMID 31354634, 2019). "Genes regulated at 4 hours included CXCR5, HLA-DQB1, HLA-DOA, and were associated with the “antigen presentation, cellular compromise, infectious disease, respiratory disease” network (network score 46)." (PMID 23544148, 2013). "Moreover, the CXCL13 not only exhibits chemotactic activity depending on CXCR5 but also acts regulatory roles in chronic inflammation, infectious diseases, autoimmune disorders, neurological conditions and tumors." (PMID 40264781, 2025). "The discovery that phenotypically unique subsets of CXCR5+ memory CD4 T cells have recall potential specific for Tfh function invites important questions for future study that will inform vaccination strategies for infectious diseases." (PMID 25699040, 2015). "It is clear that the CXCL13:CXCR5 axis is intimately involved in the initial and chronic phases of HIV infection, and, considering the central role this axis plays in humoral immunity, it is not surprising that CXCL13 has been implicated in the pathogenesis of several other infectious diseases." (PMID 31354634, 2019).
neurological disorders (3 papers, 2012 to 2024). "Of these, SH3BGRL3 has already been linked to SCZ and PSEN1, B9D2, and CXCR5 as well as DNAJB2 and were implicated in other neurological disorders." (PMID 36344995, 2022).
bacterial infection (2 papers, 2019 to 2024). "To explore the association of circulating CXCR5-expressing T-cells with the severity of bacterial infection, we determined the correlation between CXCR5 + CD8 + T-cells and serum PCT concentration." (PMID 30866951, 2019). "So, we asked whether CXCR5+ CD8+ T cells were also generated during bacterial infections in lower respiratory tract." (PMID 30866951, 2019). "However, the dynamics and role of circulating CXCR5-expressing CD8+ T-cells during bacterial infection is unknown." (PMID 30866951, 2019). "Although it is clear that CXCR5 + CD8+ T cells was involved in anti-viral immune response, surprisingly little is known about it during bacterial infections in lower respiratory tract." (PMID 30866951, 2019).
hematologic malignancies (2 papers, 2021 to 2022). "Although we did not have these samples available, tissues and PBMC from patients with hematologic malignancies who received PD‐1 ICB therapy should be analyzed to study the dynamics of CXCR5+PD‐1+ CD8 T cells to definitely prove association with response to therapy." (PMID 33098668, 2021). "In order to analyze the clinical relevance of our results, we analyzed CXCR5+PD1+ CD8 T cells in patients with hematologic malignancies with varying response rates to PD‐1 ICB." (PMID 33098668, 2021). "We analyzed the frequency and phenotype of CXCR5+PD‐1+ CD8 T cells in hematologic malignancies to determine whether they could play a similar important role of therapeutic response in those patients." (PMID 33098668, 2021). "To determine whether CXCR5+PD‐1+ CD8 T cells play a similar role in response to PD‐1 ICB in the human setting, we studied these cells in healthy individuals and in patients with hematologic malignancies with varying response rates to PD‐1 ICB." (PMID 33098668, 2021). "To determine whether CXCR5+PD‐1+ CD8 T cells could play a similar important role in humans, we studied the localization, phenotype, and functionality of CXCR5+PD‐1+ CD8 T cells in HC and patients with hematologic malignancies with varying responses to PD‐1 ICB therapy." (PMID 33098668, 2021).
cardiovascular disease (1 paper, 2025). "Receptors such as CXCR4, CXCR5, and ACKR3 not only direct B-cell trafficking but also influence their phenotype in cardiovascular disease." (PMID 40986007, 2025).
CXCR5 also shares sentences with these, for which no sentence is quoted: adenocarcinoma (3 papers); head and neck cancer (3); non-Hodgkin lymphoma (3); autoimmune thyroid disease (2); childhood asthma (2); immune disorders (2); inflammation (2); lymph node metastasis (2); lymphopenia (2); Miscarriage (2); mycosis fungoides (2); osteoarthritis (2); thyroid cancer (2); acute hepatitis B virus infection (1); Airway obstruction (1); allergic rhinitis (1); alopecia (1); ankylosing spondylitis (1); autoimmune hepatitis (1); autoimmune uveitis (1); biliary tract cancer (1); bladder cancer (1); bladder urothelial carcinoma (1); blood cancer (1); breast invasive carcinoma (1); cerebral artery (1); chronic graft versus host disease (1); chronic hepatitis C (1); chronic myelogenous leukemia (1); chronic rhinosinusitis (1).
A further 62 diseases each share a sentence with CXCR5 in 1 paper.